RNU6-344P (RNA, U6 small nuclear 344, pseudogene)
Gene: Small nuclear RNA gene on chromosome 6 (106,304,176 to 106,304,286, forward strand). Ensembl gene ENSG00000252444.
Homologues: Orthologues: chimpanzee U6 (83% identical), macaque U6 (83% identical), guinea pig U6 (64% identical). Paralogues in human: RNU6-144P (82% identical), RNU6-10P (81% identical), RNU6-16P (81% identical), RNU6-271P (81% identical), RNU6-1 (80% identical), RNU6-14P (80% identical), RNU6-2 (80% identical), RNU6-20P (80% identical), RNU6-3P (80% identical), RNU6-45P (80% identical), RNU6-4P (80% identical), RNU6-5P (80% identical), and 1286 more.